GATA3 (GATA binding protein 3)
Diseases named in the same sentence as GATA3 in open-access papers (continued):
Sharing a sentence is not in itself a finding about the gene and the disease.
tumor (continued). "In addition, outside the haemopoietic system, both FoxP3 and GATA-3 have various roles in tumour development which may be pro- or anti-tumorigenic, depending on the tumour type." (PMID 30559928, 2018). "Therefore, we hypothesize that GATA3 may contribute to the activation of macrophages in tumor tissue." (PMID 27589565, 2016). "Functional mutations in PIK3CA (odds ratio (OR)=0.58; 95% confidence interval (CI)=0.49–0.69), GATA3 (OR=0.77, CI=0.6–0.99), MAP3K1 (OR=0.52, CI=0.4–0.68), KMT2C (OR=0.69, CI=0.52–0.94) and CBFB (OR=0.56, CI=0.38–0.83) were associated with lower grade in ER+ tumours." (PMID 27161491, 2016). "Importantly, GATA3 could suppress metastasis through modifying the tumor microenvironment, such as angiogenesis and macrophage infiltrations, indicating that miR-573, the target of GATA3, may also be involved in such microenvironmental signaling." (PMID 26451614, 2015). "Immunohistochemical (IHC) profiling demonstrated that the tumor cells were strongly positive for CK7 and EMA and also showed diffuse expression of GATA3, estrogen receptor (ER), and progesterone receptor (PR)." (PMID 41769426, 2026). "While GATA3 and UPK3A exhibited the expected coordinated behavior in tumor plasma samples, reflecting their shared urothelial lineage specificity, D2 varied independently from both transcripts across all conditions." (PMID 41585944, 2026). "In contrast, GATA3 and UPK3A displayed a moderate positive correlation in tumor samples (Pearson correlation coefficient, rho, ρ = 0.50), as expected for established BLCA-associated transcripts." (PMID 41585944, 2026). "A second key finding of this study is the absence of correlation between D2 and the classical urothelial differentiation markers GATA3 and UPK3A in both non-tumor and BLCA plasma samples." (PMID 41585944, 2026). "GATA binding protein 3 (GATA3) is a nuclear zinc-finger TF that functions downstream of BRCA1 to promote DDR and suppress dedifferentiation in BC, acting as a tumor suppressor." (PMID 39860065, 2025). "For example, both GATA3–METH and GATA3–LOFDEL tumours were significantly enriched in molecular signatures of proliferation, cell cycle acceleration, DNA replication, and metastatic progression." (PMID 40585280, 2025). "IL4, secreted by Th2 cells, binds to IL4R on tumor cells, leading to activation of signal transducer and activator of transcription 6 (STAT6) and the subsequent upregulation of GATA3 and IL4 expression." (PMID 39941924, 2025). "GATA3, a key TH2 cell TF, is essential for o4R-driven tumour killing, indicating its broader role in T cell effector programs." (PMID 40804519, 2025). "Appropriate detection of the expressions of ER, PR, GATA-3, GCDFP-15, mammaglobin, CK7, and CK20 is crucial for the efficient diagnosis of tumor metastasis." (PMID 40777117, 2025). "Immunohistochemistry demonstrated tumor cells positive for CK7 and GATA-3, consistent with metastatic breast carcinoma." (PMID 41556026, 2025). "Tumor cells were positive for pancytokeratin and variably positive for EMA, GATA3, CD10, WT1, and ER." (PMID 40959354, 2025). "In both co-staining panels, nLc4 partially colocalized with GATA3- and CK5/6-positive cells, indicating that nLc4 is expressed by both luminal-like and basal-like tumor cell populations." (PMID 40706589, 2025). "GATA3 specifically was a key marker that was present in all PRNRP tumors but was negative when staining in PRCC type I and present in only one tumor of PRCC type II." (PMID 40989704, 2025). "Immunohistochemically, the tumor demonstrated a characteristic profile with strong and diffuse positivity for CK7 and GATA3, focal positivity for CK20 and TFE3, and negativity for AMACR, CA IX, and CD10." (PMID 41367859, 2025). "In contrast, at relapse, the phenotype of tumor cells shifted drastically, with only CD56, GATA-3 and ELAVL4 expression being retained, albeit with high variance at the single-cell level." (PMID 40753395, 2025).
tumor (continued). "In T-ALL, the transcription factors TAL1, GATA3, and RUNX1 form a positively connected self-regulatory loop that regulates T-cell homeostasis and directly activates MYB to facilitate tumor progression." (PMID 40083704, 2025). "Immunohistochemistry in our patient confirmed CK20 (+), CK8/18 (+), EMA (+), GATA-3 (+), and vimentin (+), and the patient’s Ki-67 (+, about 60%), and CD10 (partially +) indicated that the tumor was highly malignant and aggressive." (PMID 40083878, 2025). "The tumor was positive for spalt-like transcription factor 4 (SALL4) and GATA-binding protein 3 (GATA3), which established the diagnosis of PPC." (PMID 41625888, 2025). "Data included tumor morphology (e.g., vascular and perineural invasion), demographic variables (e.g., age, sex), and molecular markers (e.g., PD-L1, HER2, GATA3)." (PMID 41244924, 2025). "All cases were confirmed by immunohistochemistry, with tumor cells positive for CK7 and GATA-3, consistent with breast origin." (PMID 41556026, 2025). "The expression profiles of IL1β, IL10, IL18, TNF-α, TLR4, GATA3, and CD68 in HHV-infected PCa FFPE biopsies indicated an inflammatory environment conducive to immune alteration and potential tumour progression." (PMID 40430084, 2025). "In the GATA3–METH group, the majority of tumours belong to the basal-like molecular subtype (80.3%), 18.3% of tumours are HER2-enriched, only 1.4% of tumours are luminal-A, and no luminal-B tumours." (PMID 40585280, 2025). "However, by multivariate analysis, including basic clinico‐pathologic variables (histologic grade, tumor diameter, lymph node status) and ER expression, low GATA3 protein or mRNA was not independently associated with reduced disease‐specific survival (data not shown)." (PMID 41024411, 2025). "In these cases, markers such as GATA3, SOX10, mammaglobin, GCDFP15, ER, PR, HER2, and basal markers (e.g., CK5/6) should be included to provide a more complete picture of the tumor’s origin and subtype." (PMID 39518009, 2024). "Special attention regarding immunopositivity for GATA3 should be given in the differential diagnosis between SDC and high-grade salivary MEC, as both tumor entities can be positive in large areas for this marker." (PMID 38929710, 2024). "In addition to the tumor microenvironment, analyses of data from The Cancer Genome Atlas database show distinctive molecular aberrations in ILC compared with IDC, such as E-cadherin loss (66% vs. 3%), FOXA1 mutations (7% vs. 2%), and GATA3 mutations (5% vs. 20%)." (PMID 38180699, 2024). "In contrast, luminal A/B tumor cells and LM cells showed high accessibility for the ER ESR1, as well as forkhead proteins, including FOXA2 and FOXP1, GATA3 and other GATA-box TFs, and HNF1A." (PMID 39478117, 2024). "The authors demonstrated that TSLP signals through TSLPR are expressed by dendritic cells and promote GATA3+ Th2 cells and GATA3+ Tregs with enhanced immunosuppressive functions on CD8+ T cells in tumor-draining lymph nodes and tumor sites." (PMID 39201498, 2024). "The differential expression of SOX10, GATA3, and TTF-1 is usually helpful in determining the tumor origin." (PMID 38813332, 2024). "GATA3 (GATA Binding Protein 3) is a transcription factor that regulates cell differentiation and acts as a tumor suppressor in BC progression." (PMID 38505593, 2024). "Further investigation of the cistromic interplay between KDM4B, GATA3 and AR in the breast is required to definitively identify how KDM4B contributes to AR-mediated luminal programs and tumor suppression in the breast." (PMID 38317241, 2024). "Research shows that suppressive CD4+ Foxp3+ GATA3+ Treg cells proliferate in response to ST2/IL-33 signaling, both in vivo and in vitro, which aids in immunosuppression and tumor immune evasion." (PMID 40236667, 2024).
tumor (continued). "Multivariate backward linear regression with adjustment for all studied variables showed that age, sex, tumor site, tumor size, TIL count, and BCL2 score were independent variables affecting GATA3 expression." (PMID 38668712, 2024). "We previously discovered that Brca1 positively regulates GATA3 expression and that GATA3 functions downstream of BRCA1 suppressing luminal-to-basal and to mesenchymal differentiation in mammary cells as well as tumor development and progression." (PMID 38627785, 2024). "Luminal tumours were identified as KRT20+/GATA3+/FOXA1+ and basal tumours as KRT5/6+/KRT14+/GATA3−/FOXA1−." (PMID 39594166, 2024). "When evaluating the tumor microenvironment, the number of HEVs was significantly lower in PTCL‐TBX21 than in GATA3 (p = 0.032)." (PMID 38234210, 2024). "The patient with vaginal small cell carcinoma exhibited marked expression of GATA3, HER2, and PanCK at the first follow-up, which corresponded to a poor tumor response to initial chemotherapy." (PMID 36768623, 2023). "Similar to our cases, the tumor cells were diffusely positive for MUC4 and GATA3, while exhibiting focal S100 and panTrk staining." (PMID 37415052, 2023). "In addition, differentiation may result from the interaction of GATA-3 with microRNA-29b, which promotes alterations with the tumor microenvironment and inhibits metastasis by interfering with angiogenesis and extracellular matrix regulation through collagen remodeling and proteolysis." (PMID 37483298, 2023). "We observed a positive correlation of bacterial taxa, such as Corynebacterium, Prevotella, and the genus of Peptostreptococcaceae, with the expression of GATA3 (TH2) and IL-10, thereby suggesting their role as immunosuppressors in the tumor microenvironment." (PMID 37409975, 2023). "IHC showed the tumor cells were positive for CK7, Gata‐3, GCDFP‐15 (focally positive in Patients # II & IV), and negative for CA19.9." (PMID 36281523, 2023). "GATA3 and L1CAM always exhibit diffuse and strong expression, with a recent study of PRNRP showing that GATA3 and L1CAM demonstrated more heterogeneous staining in a pattern of varied intensity (weak to strong) and extent (20% to 100% of the tumor cells)." (PMID 37924117, 2023). "Control or GATA3 knockdown NS2 cells were injected into nude mice subcutaneously, and tumor growth was examined." (PMID 34980123, 2022). "ER-negative tumor amplifications were also focused on ERBB2 with less frequent amplifications of AKT1, CDKN1B, FOXO3, GATA3, KRAS, PIK3CA and TBL1XR1." (PMID 36140723, 2022). "Moreover, some reports 34, 35 indicated that GATA3 might act as a tumor suppressor." (PMID 35517412, 2022). "We then transplanted MMTV-PyMT luminal tumor cells into MFPs of NCG mice and unexpectedly found that Gata3 depleted cells resulted in a significantly smaller tumor than control cells." (PMID 34976209, 2022). "The integration of the 10 biopsies (n=20,296 cells) highlighted tumor cells (PHOX2B+, GATA3+) as well as several populations of the TME." (PMID 36054452, 2022). "These included genes consistent with pro-inflammatory immune responses (CD27, CD28, CD3e, CD8a, ICOS, ICOSLG, Pax5, TBX, GATA3, HLA-A, TNFSF14, GPR146), but also immune suppressive influences in the tumor immune microenvironment (CTLA-4, FoxP3, PD-1)." (PMID 36698398, 2022). "Next, the mRNA and protein expression levels of GATA3 and NRP1 in tumor tissues also confirmed our conjecture." (PMID 35993027, 2022).
tumor (continued). "CXCL9, CXCL10, CXCL11, and CXCR3 recruited and activated immune cells, such as CD8 + T-cells, to suppress tumor progression through CXCL9,-10−11/CXCR3 axis, and they were down-regulated in the high-GATA3 group." (PMID 35647011, 2022). "Our findings revealed that GATA3 and miR-205-p cooperatively block the transcription of MFNG leading to the inhibition of cell migration and tumor growth in vitro and in vivo." (PMID 35804829, 2022). "For the metastatic MLA in the lung in case 3, the tumor cells were positive for PAX8, GATA3, and TTF1, in accordance with the immunoprofile of the primary tumor of the uterine corpus." (PMID 35865471, 2022). "This tumor is usually positively stained with S-100, mammaglobin, CK7, MUC4, and GATA3, while in our patient the final diagnosis was based on the presence of ETV6 rearrangements which did not require immunohistochemical staining." (PMID 36186229, 2022). "Collectively, these data described a novel pathogenesis where GATA3 overexpression further positively regulated KLHL42 expression and promoted tumor progression in CTCL when KLHL42 chromatin accessibility was high." (PMID 36400759, 2022). "GATA3, FOXA1, RASSF5, PTPN6, and TRNP1, involved in the luminal markers and negative regulation of cell proliferation, are related to tumor suppression and chemotherapy resistance." (PMID 36344487, 2022). "FASLG, TNFRSF1B, GATA3, TARDBP, ZBP1, TNFRSF21, and TLR3 are mainly expressed in multiple immune cell types, and immune cells have a role in TME to inhibit tumor progression." (PMID 35899194, 2022). "The proportion of the Th2 subset (CD4+GATA3+) was decreased after RFA and cryo-thermal therapy compared to that of tumor-bearing mice, and the level of Th2 cells in the cryo-thermal treated group was much lower than that in the RFA group." (PMID 34576115, 2021). "Immunohistochemistry showed that the tumor was positive for cytokeratin 19 (CK19), S-100, vimentin, mammagloblin, gross cystic disease fluid protein 15 (GCDFP15), and GATA3." (PMID 34941172, 2021). "The H&E staining and 11 IHC markers (Ki67, P63, GATA3, KRT5/6, KRT20, E-cadherin, 34βE12, PD-L1, EGFR, Nectin4, and HER2) were used to evaluate tumor phenotype maintenance." (PMID 35432811, 2021). "Analysis of specific genes involved in CD4+ differentiation and function revealed differential methylation status of TBX21, GATA3, RORC, FOXP3, IL10 and IFNG in tumor CD4+ T-cells." (PMID 34012510, 2021). "In an in vivo study, CRISPR deletion of GATA3 reversed this effect and GATA3-KO CD8+ T-cells decelerated tumor growth." (PMID 34446084, 2021). "Regarding GATA3 and ERβ, differences in tumour histology explained part of the heterogeneity, with more GATA3 positive cases among UC and UCDD than in VH tumours." (PMID 34690921, 2021). "The C4 subset was annotated as Treg cells based on the high expression signature genes of tumor-infiltrating Tregs (FOXP3, IL2RA, IL2RB, IL2RG, IL10RA, MAGEH1, LAYN, and GATA3)." (PMID 34663810, 2021). "To verify the previously reported results, we performed immunohistochemical staining using eight paraffin-embedded tumor tissue samples to investigate the expression of CCL22, GATA-3, and IL4." (PMID 34391381, 2021). "Many claudin-low tumor cells that express mutant KRAS were CD24low/CD49fhigh and lack the expression of CD61 and GATA3." (PMID 34145248, 2021). "All tumors stained positive for GATA3 and 23% for CK5/6 (positivity: > 50% GATA3 or CK5/6 positive cells in the tumor parenchyma)." (PMID 33863885, 2021). "We also assessed the correlations between the expression of SLC39A6 and other well-characterised ER-related markers that have been identified as signature genes in ER + tumours, including FOXA1 and GATA3." (PMID 34453638, 2021). "In tumor epithelium and stroma, most CD4+ T cells identified had either a Th2 (GATA-3+CD3+CD8-) or Treg (FOXP3+CD3+CD8-) phenotype, whereas only low numbers of Th1, Th17, and Tfh cells were observed." (PMID 34868011, 2021).
tumor (continued). "Through a systems medicine approach, it was determined that hub biomolecules, AR, GATA2, miR-124, TOR1AIP1, ESR1, EGFR, STAT1, miR-192, GATA3, COL1A1, in tumor microenvironment generic network." (PMID 33907495, 2021). "From the CRC network, only ASCL1 emerged from this analysis, given its different dynamic expression during murine TH-MYCN-driven tumor formation compared to HAND2, PHOX2B, GATA3 and ISL1." (PMID 34638267, 2021). "It was also found that in the tumor tissue of the oe-USP21 group, USP21, GATA3, and MAPK1 were all pronouncedly highly expressed." (PMID 33791299, 2021). "In our cases, immunostaining revealed that the tumor was positive for CK19, S-100, vimentin, mammaglobin, GCDFP15, GATA3, and MUC4." (PMID 34941172, 2021). "With increasing levels of tumor PD-L1, the expression of transcription factors for Th1, Th2, or M1 macrophages, including NFKB1, GATA3, HIF1A, STAT4, TBX21, IRF8, and STAT1, was downregulated." (PMID 33754038, 2021). "Immunohistochemical analysis showed that the tumor cells were positive for Gross cystic disease fluid protein (GCDFP)-15, mammaglobin and GATA3." (PMID 33782642, 2021). "Elevated eATP in the tumour microenvironment has been shown to facilitate EMT, cell migration and metastasis, with GATA3 functioning in an anti-metastatic manner by promoting eATP hydrolysis." (PMID 33298139, 2020). "The reactivity for CK7, GATA3, CK5/6, 34βE12, and Uroplakin III further supported the possibility that these tumor cells were undergoing urothelial metaplasia." (PMID 32164751, 2020). "In another study, the basal/squamous cell carcinoma-like group was reported to show a tumor phenotype with high KRT6 and KRT14 and low FOXA1 and GATA3 expression by IHC." (PMID 33365265, 2020). "GATA3 interacts and stabilizes the HIF protein and increases tumor cell migration and invasiveness under hypoxic conditions." (PMID 32850359, 2020). "Immunohistochemical staining revealed the tumour cells to be AE1/AE3, CK7, GCDFP-15, E-cadherin, androgen receptor (AR) stain and GATA3 positive." (PMID 33054772, 2020). "Immunohistochemical staining revealed the tumour cells to be AE1/AE3, CK7, GCDFP-15, E-cadherin, androgen receptor stain and GATA3 positive." (PMID 33054772, 2020). "Immunohistochemical (IHC) staining was performed for GATA‐3 in the brain and lung, and for CK5/6 in tumor tissues." (PMID 33133558, 2020). "The finding of elevated GATA3 in women and decreased Tbet in men (compared to normal tissues) is intriguing, and would be consistent with a stronger Th2, Th1 and/or CD8 anti-tumour response in women." (PMID 32451467, 2020). "Therefore, GATA3 increment in tumor cells may be a helpful method to treat basal-like TNBC." (PMID 31013830, 2019). "A study of matched normal, early neoplasia and carcinoma from a cohort of 25 women identified elevated expression of ERBB2, FOXA1, and GATA3." (PMID 31248446, 2019). "By contrast, 95% and 76% of evaluable cases stained for GATA3 and FOXA1 in >80% of tumor cells, respectively." (PMID 30699951, 2019). "When analyzing the Tc2 transcription factor, GATA-3, we found 1.6 times upregulation in CD8+ T cells derived from SN (p<0.01) and 2 times upregulation in CD8+ T cells from tumor when compared to from PBMC (p<0.01)." (PMID 29966014, 2018). "We found that the Tc2 transcription factor, GATA-3, was upregulated in CD8+ T cells from SN and tumor, with concomitant downregulation of the Tc1 transcription factor, T-bet." (PMID 29966014, 2018). "Immunohistochemical analysis indicated positivity of the tumour cells for vimentin, CK, EMA, CEA, CKH, GATA3, and P63 and negativity for Desmin, S-100, and CK20." (PMID 29653574, 2018).